APOE (apolipoprotein E)
Diseases named in the same sentence as APOE in open-access papers (continued):
Sharing a sentence is not in itself a finding about the gene and the disease.
glioma (continued). "Indeed, an increase in macrophages expressing high levels of Spp1, ApoE, Apoc1, Lgals3, and Gpnmb has been documented in glioma models, with high‐grade gliomas exhibiting a greater abundance of these macrophages compared to low‐grade gliomas." (PMID 40395129, 2025). "To this end, we compared the survival rates and histomorphological features of GL261 glioma cell lines in C57BL/6 wild‐type (WT) mice and ApoE‐knockout (ApoE−/−) mice." (PMID 40662483, 2025). "A significant increase in apolipoprotein E (APOE) and apolipoprotein A1 (APOA1) protein levels in the CSF of GBM patients has been reported compared to those in the CSF of patients with low-grade gliomas." (PMID 39062515, 2024). "Moreover, the similarity with ApoE internalization and the determinant role of ApoE in guaranteeing tumor cell proliferation, angiogenesis, and metastasis, suggested that this internalization route might be preferential in the uptake by target glioma cells." (PMID 36235232, 2022). "The same three peptides of APOE and APOA1 gave a cumulative fold change of 1.59 and 2.69 respectively in GBM when compared to low grade glioma." (PMID 34055594, 2021). "Three peptides of 5 Proteins which includes APOA1, APOE, PTGDS, VTN and C3 were monitored for both Meningioma and Glioma samples." (PMID 34055594, 2021). "Our own work identified APOA1 and APOA4 in the proteomic analyses of EVs derived from human medulloblastoma cell lines and murine glioma cells, with APOB and APOE identified in EVs from other tumor cell lines (Graner, unpublished data)." (PMID 34360613, 2021). "Our results indicate that the absence of ApoE remarkably speeds up glioma growth and encourages the invasive nature of tumour cells." (PMID 40662483, 2025). "Accordingly, ApoE-coated nylon-3 polyplexes showed significantly increased uptake and gene silencing in U87 glioma cells but no benefit in vivo." (PMID 38087181, 2024). "In another study, polycarbonate vesicles were fabricated from the self-assembly of poly (ethylene glycol)-polycarbonate-spermine and functionalized with apolipoprotein E peptide (ApoE) as a targeting agent that can cross the BBB and accumulate inside the glioma." (PMID 35954362, 2022). "After internalization into glioma cells, SAP could be released from ApoE‐CP in response to the high GSH concentration, leading to the DNA damage." (PMID 33977060, 2021). "ApoE‐CP could specifically bind to LDLRs and mediate superb BBB crossing and further target the glioma cell, functioning as a dual‐targeting delivery system." (PMID 33977060, 2021). "Treatment with SAP‐loaded ApoE‐CP efficiently inhibited the growth of U87 glioma without eliciting any severe adverse effect and significantly improved survival benefits." (PMID 33977060, 2021). "Importantly, PTX/Aβ-CN-PMs exhibited better anti-glioma effects and tissue distribution profile with rapid accumulation in glioma tissues in vivo and prolonged median survival of glioma-bearing mice compared to those associated with PMs without the ApoE protein corona." (PMID 34963449, 2021).
glioma (continued). "Researchers hypothesize that the absence of the ApoE gene could result in alterations in certain crucial signalling pathways or immune responses, consequently facilitating the accelerated growth of gliomas." (PMID 40662483, 2025). "Here, we show that intravenous (i.v.)or intranasal (i.n.)administration of apolipoprotein E peptide (ApoE)‐directed polymersome CpG nanoformulation (t‐NanoCpG) mediates efficient brain delivery of CpG, inducing strong immunotherapy of highly malignant murine LCPN glioma." (PMID 35253404, 2022). "The activated LXRs enhances cholesterol efflux and decreases cholesterol influx by upregulating ApoE, resulting in the cholesterol de novo synthesis and the alteration of cholesterol homeostasis in IDH-1 mutant glioma cells, which further contributes to glioma progression." (PMID 36506554, 2022). "In addition, PS‐80‐modified nanoparticles would be ineffective for these glioma patients who do not express or only express low level of ApoE proteins." (PMID 29956460, 2018). "The markers for this population are largely expressed only in glioma cells (e.g., NFIB, MAP1B, TUBB2B) and they express low levels or have no expression of myeloid/immune markers (CD74, APOE, HLA genes, and CD45)." (PMID 40588233, 2025).
hyperhomocysteinemia (26 papers, 2005 to 2025). A serious metabolic condition caused by mutations in the MTHFR gene, medications, or nutritional deficiency. "Likewise, in a model of hyperhomocysteinemia (HHcy)-accelerated plaques in apolipoprotein E-deficient (apoE–/–) mice abatacept-treatment reversed plaque development with reduced T cell-dependent macrophage recruitment and IFN-γ/Interleukin-2 secretion." (PMID 39039301, 2025). "Further reports on Sprague-Dawley rats and ApoE knockout mice with induced hyperhomocysteinemia and 2 to 6-fold elevated SAH levels specifically associated the DNA hypomethylation with repetitive B1 elements, the murine equivalent of human Alu repetitive elements." (PMID 26974671, 2016). "Whether MR-induced hyperhomocysteinemia causes vascular damage in ApoE-KO mice remains to be investigated." (PMID 25744495, 2015). "HDAC1 activation has been associated with a decrease in global H3K9 acetylation in the aortas of apolipoprotein E (ApoE) knockout mice treated with a high methionine diet to induce hyperhomocysteinemia, promoting lipid accumulation in foam cells." (PMID 37298289, 2023). "We used ApoE−/− mice to construct an animal model of hyperhomocysteinemia As, and stimulated VSMC with 100 μmol/L Hcy in vitro." (PMID 37945738, 2023). "A previous report indicated that shikonin attenuates hyperhomocysteinemia‐induced activation of CD4+ T cells in ApoE−/− mice." (PMID 34646528, 2021). "For example, whereas plasma Hcy appeared insubstantial to CSF tau in the total sample, hyperhomocysteinemia was relevant to CSF tau in the APOE ε4 carriers." (PMID 28623948, 2017). "Consistent with other models used in this study, ApoE-KO MR mice had lower body weight with hyperphagia, decreased absolute heart weight, and higher heart-to-body weight ratio (w/w) as well as hyperhomocysteinemia compared with ApoE-KO CF mice." (PMID 25744495, 2015). "Our study showed that MR increased the heart-to-body weight ratio (w/w) and induced hyperhomocysteinemia in young, old, and apolipoprotein E KO (ApoE-KO) mice." (PMID 25744495, 2015). "Experimentation has shown isolated hyper-homocysteinemia to be atherogenic in cystathionine β-synthetase and apolipoprotein-E double knock-out mice." (PMID 15626644, 2005). "In this study, hyperhomocysteinemia and higher heart-to-body weight ratio (w/w) were evident in young, old, and ApoE-KO MR mice; however, cardiac function and responses to β-adrenergic stimulation varied according to non-invasive ECG tests performed on conscious mice." (PMID 25744495, 2015). "Additionally, hyperhomocysteinemia in ApoE-KO mice is associated with altered lipid metabolism without the progression of atherosclerotic lesions." (PMID 25744495, 2015). "Other studies reported that IMD expression decreased in the plasma, cardiac tissue, adipose tissue, and aortic root atherosclerotic lesions of db/db mice, HFD-induced obese mice, hyperhomocysteinemia mice, HFD-fed ApoE-/- mice, and diabetic rats." (PMID 39338366, 2024).
late-onset Alzheimers disease (26 papers, 2006 to 2025). This is the most common form of the disease, which happens to people age 65 and older. "Apolipoprotein-E (APOE) is the strongest genetic risk factor for late-onset Alzheimer’s Disease (LOAD, age of onset after 65y), which accounts for more than 90% of all AD cases." (PMID 38035273, 2023). "APOE e4 is the most strongly established genetic risk variant for late-onset Alzheimer’s disease (LOAD) and APOE plays a critical role in the genetic etiology of AD also because of gene dysregulation." (PMID 37238925, 2023). "Another type of AD is late-onset Alzheimer’s disease (LOAD), which is related to the presence of alleles of the apolipoprotein E gene (APOE), localized on the 19q13.2 chromosome." (PMID 35563001, 2022).
lipid metabolism disorder (26 papers, 2015 to 2025). "A large number of studies have shown that PM2.5 can cause serum lipid metabolism disorders in ApoE−/− mice, promote the phagocytosis of ox-LDL by macrophages through surface scavenger receptors and induce foam cell formation." (PMID 37722877, 2023). "Totally, these results suggested that, for T2DM subjects, the carrying of ApoE ε4 allele implicate a predisposition of lipid metabolism disorder and cognition decline." (PMID 29896424, 2018). "Investigating the spectrum of APOE variants may advance our understanding of the genetic basis of FD and underscore the important role of APOE gene sequencing in patients with lipid metabolism disorders." (PMID 39684364, 2024). "Therefore, ApoE−/− mice are often used to study lipid metabolism disorders and diseases caused by lipid metabolism disorders in various organs such as liver, kidney, artery, and brain nerves." (PMID 35836833, 2022). "Furthermore, ApoE genetic variation-associated lipid metabolism disorder was suggested to be involved in the pathological progression of AD." (PMID 29559956, 2018). "The increased ApoE expression detected in the kidneys of rats investigated in this study is thus evidence that these rats suffer from lipid metabolism disorder." (PMID 34869779, 2021). "APOE and APP are the most commonly accepted risk genes for early onset of AD, suggesting the involvement of lipid metabolism disorder in AD progression." (PMID 32224504, 2020). "The major new finding of the present study was that EGCG, a major ingredient of green tea, modulated high-fat-mediated hepatic TTC39B expression, which were responsible for lipid metabolism disorder in ApoE-/- mice." (PMID 29593532, 2018). "Investigating the spectrum of APOE variants may advance our understanding of the genetic basis of FD and underscore the importance of APOE gene sequencing in patients with lipid metabolism disorders." (PMID 39684364, 2024). "et Zucc., can activate the activities of ABCA1, ABCG1, and ApoE with PGC-1α as the central target to inhibit lipid deposition in cells and improve lipid metabolism disorder in the kidney, thus preventing or delaying the occurrence and development of DN." (PMID 34485530, 2021). "Through a concurrent 12-week swimming training, lipid metabolism disorder and IR in the HFD ApoE-KO mice were significantly improved." (PMID 30611282, 2019). "It was also found that the absence of ApoE aggravated lipid metabolism disorders and oxidative stress in aging mice." (PMID 36188475, 2022). "In conclusion, we showed that TMP could inhibit the progress of As and ameliorate lipid metabolism disorder by downregulating PAQR3 and inhibiting SCAP/SREBP-1c signaling pathway in ApoE−/− mice fed with a high-fat diet." (PMID 28491104, 2017).
liver disease (26 papers, 2010 to 2025). "ApoE plays a very important role in the infectious cycle of two major hepatitis viruses causing chronic infections leading to severe liver disease." (PMID 35409035, 2022). "Interestingly, possession of APOE-ε4 is protective against chronic hepatitis C, and lowers the risk of developing severe liver disease from the virus compared to APOE-ε3." (PMID 29559905, 2018). "This information may be useful in considering simple, low-toxicity combinations to reduced progression of cardiometabolic disease, including in patients with previous liver disease, liver injury, or mutations in the ApoE gene diminishing their response to statins." (PMID 40779455, 2025). "APOE ε4, body mass index (BMI), metrics of kidney function (eg, estimated glomerular filtration rate [eGFR]), and liver disease were derived from electronic health records." (PMID 41447112, 2025). "APOE ε4, body mass index (BMI), metrics of kidney function (e.g., eGFR), and liver disease were derived from electronic health records." (PMID 40894158, 2025). "As one of the important molecules in the lipid metabolism pathways, apoE has been found to have key roles in various liver diseases leading to HCC." (PMID 38976030, 2024). "The human samples were used as proof-of-principle type experiments to confirm our findings in mice by showing the existence of the C1q-ApoE complex formation within different clinically important human liver diseases." (PMID 36304458, 2022). "Nevertheless, an earlier study about the effect of ApoE polymorphism and the outcome of HCV infection in the United States indicated that the E4 allele protected against severe liver disease in the HCV-gt1 American cohort." (PMID 33924242, 2021). "In particular, apolipoprotein E-knockout (ApoE–/–) mice represent a valid animal model suitable for the assessment of liver disease." (PMID 33291840, 2020). "The other four are also highly relevant for liver disease: APOE (apolipoprotein E), dipeptidyl peptidase‐4 (DPP4), TGFBI (transforming growth factor‐beta‐induced protein ig‐h3), and aminopeptidase N (ANPEP)." (PMID 30824564, 2019). "The role of ApoE−/− itself on vascular alterations following increase of portal hypertension cannot be excluded." (PMID 26263022, 2015). "The association of APOE, HCV infection, and SARS-CoV-2 in liver disease is complex, thus the better understanding of the interrelated injury causal-effects, such as direct viral damage, drug-induced liver injury, hypoxia and microthromboses requires novel clinic and basic research strategies." (PMID 35359998, 2022). "However, the more pronounced fibrosis in ApoE−/− mice fed WD suggests fibrosis as a major factor leading to portal hypertension." (PMID 26263022, 2015). "Additionally, DeKroon and co-workers reported an anti-apoptotic role of ApoE, while others reported that ApoE protects against severe liver disease in hepatitis C virus infection." (PMID 24070255, 2013). "However, no significant impact of apoE genotype on non-HCV associated liver disease has been established." (PMID 20109174, 2010). "For example, specific alleles in variants in/near APOE, LIPC, MLXIPL, and TM6SF2 promote liver disease while resulting in a favorable serum lipid profile of decreased TG/LDL or increased HDL, suggesting they may cause liver disease by sequestering lipids/metabolites in the liver." (PMID 33547301, 2021). "Remarkably, in this unbiased analysis, four clinical markers used in liver disease—ALT, AST, ALP, and GGT—clustered into a single group together with a panel of five proteins of special interest—PIGR, DPP4, ANPEP, TGFBI, and APOE." (PMID 30824564, 2019). "While the C57BL/6 and ApoE−/− mouse models are widely used to study gene expression changes in liver disease and metabolism, currently there are no validated stably expressed endogenous genes in these models, neither is it known how gene expression varies within and across liver lobes." (PMID 29795401, 2018).
injury (25 papers, 2008 to 2025). Damage inflicted on the body as the direct or indirect result of an external force, with or without disruption of structural continuity. "ApoE4 carriers show less motor recovery during rehabilitation than individuals with other ApoE alleles, as determined by applying the American Spinal Injury Association (ASIA) motor score during rehabilitation." (PMID 33679326, 2021). "We examined whether childhood trauma, apolipoprotein E isoforms and viral protein R (Vpr) variants were associated with change in cognitive performance." (PMID 31881924, 2019). "One implication of these studies is that ApoE genotype can alter the prognosis for recovery from CNS trauma, likely both SCI and TBI." (PMID 41278832, 2025). "In animal models of brain injury, ApoE and ABCA1 expression were increased, presumably to facilitate this transport." (PMID 34830135, 2021). "The further development of apoE based therapeutics represents a promising therapeutic strategy in the treatment of acute brain injury." (PMID 28429734, 2017). "Previous studies showed that a deficiency of ApoE may exacerbate brain edema after brain trauma by promoting BBB breakdown and increasing the injury susceptibility of the BBB17, 22, which demonstrates that ApoE may influence BBB integrity after TBI." (PMID 28751738, 2017). "ApoE is the major apolipoprotein synthesized in the CNS, which not only serves as an important mediator of cholesterol and lipid transport, but also affords neuroprotective effects via multiple mechanisms including anti-inflammatory, anti-excitotoxic, and anti-oxidant properties after brain injury." (PMID 32466767, 2020). "Indeed, apoE−/− mice display progressive, age-dependent BBB leakage which appears to be exacerbated with injury, suggesting that a lack of apoE may increase BBB dysfunction and edema following brain trauma." (PMID 29618365, 2018).
non-alcoholic fatty liver disease (25 papers, 2017 to 2026). "Alox15, the gene encoding for 12/15-lipoxygenase (12/15-LOX), is markedly up-regulated in livers from apolipoprotein E-deficient (ApoE2/2) mice, which spontaneously develop nonalcoholic fatty liver disease." (PMID 36830070, 2023). "The study was aim to reveal the relationship between Apolipoprotein E gene polymorphism and nonalcoholic fatty liver disease in Southern China." (PMID 34664321, 2021). "Similarly, a proteomic study revealed that carnosine treatment in rats, a natural dipeptide known for its protective effects against oxidative stress in nonalcoholic fatty liver disease (NAFLD), led to the downregulation of PLIN2 and ApoE." (PMID 41404624, 2025). "Our results showed that LRM significantly reduced fatty acids accumulation due to increased oxidation and reduced synthesis, inflammation, and ROS production in hepatocytes, resulting in alleviating nonalcoholic fatty liver disease in ApoE−/− mice, which is independent of obesity." (PMID 32566176, 2020).